IL10 (interleukin 10)
Diseases named in the same sentence as IL10 in open-access papers (continued):
Sharing a sentence is not in itself a finding about the gene and the disease.
tumor (continued). "The combination of all three inhibitors resulted in a tumor microenvironment characterized by increased IFNγ-producing CD4+ T cells, decreased CD4+FOXP3+ T regulatory cells (Tregs), and decreased IL-10-producing CD4+ T cells." (PMID 40904502, 2025). "CAFs within the stroma produce large quantities of extracellular matrix proteins in response to cytokines like IL-10 and TGF-β secreted by tumor cells." (PMID 40647513, 2025). "B cells produce cytokines like IL-10 and transforming growth factor β (TGF-β) to aid in tumor progression, while also acting as tumor suppressors due to the production of IFN-γ." (PMID 41020852, 2025). "Meanwhile, IL-10 and TGF-β skew the immune microenvironment toward suppression, allowing tumor cells to evade immune destruction." (PMID 41007766, 2025). "Immune alterations also include increased CD4 +/CD8 + and IL-17 + γδ T cells, and elevated expression of immunosuppressive (IDO1, IL-10, PD-L1) and oncogenic (AKT1, STAT3, CXCR4) genes with key roles in tumor progression and immune evasion." (PMID 40924302, 2025). "On the one hand, pro-tumor TAMs express high level CD206 and produce immunosuppressive cytokines, such as IL-10 and TGF-β, to directly or indirectly inhibit T cell proliferation and activation." (PMID 39744236, 2025). "These M2-type TAMs secrete factors including transforming growth factor-β (TGF-β), interleukin-10 (IL-10), arginase-1 (ARG1), and vascular endothelial growth factor (VEGF), which further suppress anti-tumor immunity and promote angiogenesis." (PMID 41488637, 2025). "In active OpdA-treated tumor-bearing mice, there was a significant increase in the percentages of tumor-specific CD4+/IFN-γ+ and CD4+/IL-10+ T lymphocytes in the spleen." (PMID 41019059, 2025). "Factors such as TGF-β, IL-10, and VEGF, released by tumor cells, inhibit DC maturation, impairing their antigen-presenting capability." (PMID 40420798, 2025). "It is through kinds of signaling molecules that TAMs directly influence tumor cell development, invasion, and metastasis and help create an environment conducive for tumor cell growth, such as TGF‐β, IL‐10." (PMID 39927632, 2025). "Growth factors and cytokines (IL-6, IL-7, IL-10, GM-CSF, VEGF, TGF-β) are produced by the surrounding stroma and also by tumor cells, and induce, by coupling to their cell membrane receptors, JAK-STAT3 activation." (PMID 41463071, 2025). "These macrophages secrete immunosuppressive cytokines, such as IL-10 and TGF-β, which not only inhibit the function of CD8+ T cells but also promote a microenvironment that favors tumor progression." (PMID 40136347, 2025). "Conversely, M2-type macrophages primarily release immunosuppressive factors (IL-10, VEGF, Arg-1) that facilitate tissue remodeling, promote angiogenesis, and ultimately support tumor progression." (PMID 40426851, 2025). "USP9X knockdown reduces tumor growth, lowers TRRAP expression, and shifts macrophages toward pro-inflammatory states by decreasing IL-10 and TGF-β1 secretion." (PMID 40427130, 2025). "M2 macrophages can secrete IL-10 and TGF-β mediators, which promote tumor progression and immune evasion." (PMID 41221277, 2025). "In the tumor microenvironment, increased concentrations of TGF-β, IL-10, and PGE2 hinder the effective maturation of DCs." (PMID 40333202, 2025). "This study aimed to explore the relationship between the presence of F. nucleatum and the expression of inflammation-related genes (IL6, IL1B, IL10, IL17, TNF) in tumor and matched normal tissue of Kazakhstani CRC patients." (PMID 41267807, 2025). "Immunosuppressive cytokines such as IL-10 and TGF-β facilitated tumor immune evasion, while IL-17 promoted inflammation and angiogenesis." (PMID 41007766, 2025).
tumor (continued). "Tumor and stromal cells release an array of immunosuppressive mediators, including transforming growth factor-beta (TGF-β), interleukin-10 (IL-10), indoleamine 2,3-dioxygenase (IDO), and prostaglandin E2 (PGE2)." (PMID 40564018, 2025). "For instance, activation of TLR4 can promote the secretion of pro‐inflammatory cytokines and chemokines, such as IL‐6, IL‐10, and TNF‐α, which can create an immunosuppressive microenvironment that facilitates tumour growth and metastasis." (PMID 40696496, 2025). "Adiponectin has been shown to inhibit tumor cell proliferation through activation of the AMPK–PPARα signaling pathway, IL-10 suppresses proinflammatory cytokine expression, and FGF21 plays a role in modulating oxidative stress and immune homeostasis." (PMID 40731020, 2025). "Further enrichment and cell interaction analysis revealed that these two tumor subclones shared similar activities in the ACTIVIN and IL1 signaling pathways, while type_1_2 showed higher IL-10 and calcitriol activity with other spots." (PMID 41373592, 2025). "Other reported proteins that were expressed in tumor-derived exosomes including TRAIL, a death receptor ligand; in addition to inhibitory cytokine TGF-β1, they also contain IL10, prostaglandin E2 (PGE2), and PD-L1, which is a check point receptor ligand." (PMID 39857258, 2025). "NF-κB signaling is triggered in macrophages by tumor-derived cytokines such as TNF-α and IL-1β, further enhancing the production of IL-6 and IL-10, that further promote tissue remodeling and angiogenesis." (PMID 40160820, 2025). "Growth factors such as EGF, VEGF, FGF, IL‐10, IL‐6, TNF‐α, IFNγ produced by TAMs and NKs and miRNAs carried in tumour‐derived EVs promote tumour proliferation by activating pathways such as RAS–RAF–MEK–ERK–MAPK and PI3K–AKT–mTOR." (PMID 40525649, 2025). "IL-10 induces the STAT1 pathway, increases granzyme and IFN-γ expression, enhances immune response, and promotes tumor cell apoptosis." (PMID 41142594, 2025). "For instance, SASP‐induced secretion of prostaglandin E2 (PGE2) and IL‐10 was reported to downregulate MHC‐II and costimulatory molecules on DCs, thereby hampering the priming of naïve T cells and limiting the efficacy of tumor‐specific immune responses." (PMID 40926366, 2025). "M1 macrophages produce proinflammatory cytokines such as TNF-α and IL-12, which support antitumour immunity, whereas M2 macrophages secrete immunosuppressive cytokines such as IL-10 and TGF-β, which promote tumour growth and immune tolerance." (PMID 41163221, 2025). "The TME is rich in immunosuppressive cells, such as Tregs, MDSCs, and TAMs, which weaken the anti-tumor functions of effector T cells by secreting immunosuppressive factors (such as TGF-β, IL-10)." (PMID 40094019, 2025). "This inflammatory state promotes the release of cytokines (e.g., IL-1β, IL-6, IL-10, IL-18, TNF-α) and growth factors that facilitate tumor cell proliferation, invasion, and angiogenesis, while simultaneously impairing immune surveillance." (PMID 41114747, 2025). "First, CAFs secrete a variety of immunosuppressive cytokines and chemokines, such as TGF-β, IL-10, and PGE2, which inhibit the proliferation and activation of T cells, reducing their ability to recognize and kill tumor cells." (PMID 40104498, 2025). "Multiple factors known to be involved in tumor progression and regulation of immunity including MHC class I, PD-L1, IL-8, IL-10, and COX-2 were differentially expressed between 786-O and pVHL spheroids." (PMID 40736709, 2025). "The secretion of IgG by plasma cells can activate Fc gamma receptors (FcγR) on macrophages, leading to production of IL-6, IL-10, and CCL20 while suppressing the anti-tumor immune response." (PMID 40453088, 2025). "M2 macrophages then secrete IL-10 and TGF-β, further suppressing immune responses and supporting tumor cell survival and metastasis." (PMID 40486614, 2025).
tumor (continued). "By secreting IL-10 and TGF-β, TAMs inhibit the proliferation and activation of T cells, thereby dampening the anti-tumor immune response." (PMID 41180630, 2025). "Immunosuppressive cytokines such as IL-10 and TGF-β create an immune-evasive milieu, promoting tumor survival and proliferation." (PMID 40309351, 2025). "In addition, tumour cells can release a variety of cytokines and chemicals such as IL‐10, TGF‐β, PGE2 and IDO to induce apoptosis in CD8+ T cells, and these cytokines and chemicals may induce apoptosis in CD8+ T cells through a variety of signalling pathways and routes." (PMID 40356050, 2025). "Molecular analyses supported these findings, showing significant downregulation of tumor-promoting genes, including VEGF, MMP-9, and IL-6, as well as upregulation of the anti-inflammatory cytokine IL-10." (PMID 40808199, 2025). "It reflects a dynamic interaction between anti-tumor factors (e.g., IL-12, IFN-γ) and pro-tumor factors (e.g., IL-10, IL-23)." (PMID 39934876, 2025). "In drug loading, modified MSCs such as TRAIL, interleukin-10, microRNAs, or prodrug-converting enzymes can achieve precise localized release via CXCR4-mediated tumor-homing mechanisms." (PMID 41301162, 2025). "CD4+ Treg lymphocyte subsets, often present in the tumor, promote EMT by secreting IL-10 and TGF-β, which activate signaling pathways supporting the loss of epithelial features and acquisition of a mesenchymal phenotype by tumor cells." (PMID 40362280, 2025). "t-SNE visualization indicated a significantly higher distribution density of FOXP3, IL10, TGF-β1, and CTLA4 positive cells in the tumor group compared to the normal group, with gene expression concentrated in immune subpopulations like T cells." (PMID 41438510, 2025). "NK cell proliferation and antitumor activity are reduced by the release of different immunosuppressive substances by tumor cells, including prostaglandin E2, indoleamine 2,3-dioxygenase (IDO), IL-10, TGF-β and vascular endothelial growth factor (VEGF)." (PMID 40727443, 2025). "Lactic acid can also promote M2 polarization and regulate the tumor microenvironment by secreting cytokines such as TGF-β and IL-10." (PMID 40557160, 2025). "M2-type TAMs are characterized by their immunosuppressive roles and their ability to secrete a variety of cytokines, including IL-10 and TGF-β, which can inhibit the functions of immune cells such as T cells and NK cells, thus promoting tumor immune evasion." (PMID 41394878, 2025). "T cell accumulation was significantly higher in the spleen and within the tumor microenvironment, with elevation in activation markers such as Interleukin-17, CD69, NKG2D, and FasL and a decrease in Interleukin-10 and FoxP3 expression." (PMID 41096863, 2025). "Tregs secrete immunosuppressive cytokines such as IL-10 and TGF-β, inhibiting effector T-cell activity and enabling tumor cells to escape immune surveillance." (PMID 40557321, 2025). "Key cytokines of interest include IL-6, TNF-α, IL-1β (as prototypical pro-tumor inflammatory cytokines), as well as others such as IL-8 (CXCL8), IL-10, and IL-17, which together shape the tumor immune microenvironment." (PMID 41007766, 2025). "Conversely, elevated levels of IL-10 within the TME can impede effective anti-tumoral immune responses, thus facilitating immune evasion and tumor progression." (PMID 41376630, 2025). "IL-10 production is induced after high-risk HPV infection, and elevated IL-10 levels have been found in cervical exudate in high-risk HPV patients.There is controversy surrounding IL-10’s multifaceted role, as it may both suppress and promote tumor initiation and progression." (PMID 41142594, 2025). "M2-like TAMs secrete immunosuppressive cytokines (e.g. IL-10, TGF-β) and growth factors (e.g. VEGF) that blunt cytotoxic T cell activity and support tumor growth, effectively creating a protective niche for the tumor." (PMID 41164132, 2025).
tumor (continued). "This phenotype is characterized by the secretion of immunosuppressive cytokines like IL-10 and TGF-β, which dampen the anti-tumor immune response and promote tumor growth." (PMID 40486614, 2025). "By producing cytokines, such as interferon, TNF, IL-10, IL-12, and VEGF, controlling the PD-1/PD-L1 signaling axis, and suppressing anti-tumor immune responses, M2 TAMs attract immunosuppressive cells and cause the depletion of cytotoxic T cells." (PMID 40426851, 2025). "Sphingosine kinase 1 (SK1) inhibitors reduce immunosuppressive cytokines such as TGF-β and IL-10, while enhancing CD8+ T cell function and the tumor’s response to ICI." (PMID 40872475, 2025). "Numerous studies indicate that Breg cells infiltrate human malignancies and suppress anti-tumor immune responses through the expression of immune checkpoint molecules (PDL1) and immunosuppressive cytokines (IL10, IL35, and TGFβ)." (PMID 41019045, 2025). "Conversely, Treg-derived IL-10 and IL-35 cooperatively upregulate the expression of multiple inhibitory receptors and drive BLIMP1-dependent exhaustion of tumor infiltration CD8+ T cells, further impeding antitumor immunity." (PMID 41268548, 2025). "M2 macrophages secrete anti-inflammatory factors (e.g., IL-10, TGF-β) that suppress tumor-specific immunity and promote tumor survival and metastasis." (PMID 41376630, 2025). "cultured TILs express IFN-γ, IL-4, IL-5, TNFα, IL-8, IL-10- and, to a lesser extent, IL-2 mRNAs while, in the corresponding tumor samples only TNF-α, IL-8 and IL-10- transcripts were expressed." (PMID 40092980, 2025). "Tumor-derived exosomes carry TGF-β1 and IL-10, which increase regulatory T cells (Tregs), reducing immune response against tumors." (PMID 39857258, 2025). "This analysis highlighted the consistent induction of pro-inflammatory cytokines such as IL-1β, IL-6, IL-8, IL-10, IL-17A/F, and TNF, which are known to play central roles in immune activation, macrophage polarization, and tumor–immune cell crosstalk." (PMID 41514627, 2025). "Hypoxic conditions promote HMGB1 release from necrotic tumor cells, which in turn recruits M2-like macrophages and creates an IL-10 rich milieu through RAGE signaling, ultimately facilitating tumor growth and metastasis." (PMID 41465435, 2025). "In tumor-associated macrophages (TAMs), YTHDF2 is upregulated via the IL-10/STAT3 pathway and suppresses IFN-γ/STAT1 signaling, maintaining a pro-tumor phenotype." (PMID 41403953, 2025). "Current understanding posits that tumor-secreted factors such as TGF-β, IL-10, and macrophage colony-stimulating factors drive the differentiation of monocytes–macrophages toward the M2 phenotype." (PMID 41463331, 2025). "Lastly, Tregs secrete tumor-promoting cytokines such as TGF-β, IL-10, and IL-6, whereas tumor-suppressing CD8+ and NK cells secrete IFN-γ, TNF-α, etc.." (PMID 41369383, 2025). "This expansion is orchestrated by the tumor microenvironment, where immunosuppressive cytokines such as TGF-β and IL-10 induce naïve T cell conversion into Tregs, and chemokines like CCL22 mediate recruitment via CCR4 signaling." (PMID 41181112, 2025). "Treg cells secrete inhibitory cytokines such as IL-10, IL-35, and TGF-β, which collaboratively regulate the expression of specific inhibitory receptors and exhaustion-related genes in tumor-infiltrating CD8+ T cells." (PMID 41368628, 2025). "In contrast, Treg cells in the tumor microenvironment mainly secrete immunosuppressive cytokines such as transforming growth factor-β (TGF-β) and interleukin-10 (IL-10) to inhibit the activity of CTL cells and other immune cells." (PMID 39861694, 2025). "In contrast, M2 macrophages exert immunosuppressive functions, producing IL-10, transforming growth factor (TGF)-β, PD-L1, and vascular endothelial growth factor (VEGF), which support tumor progression, tissue remodeling, angiogenesis, and metastasis." (PMID 40565133, 2025).
tumor (continued). "The TIMER2.0′ Immune Association’ module analysis indicated a significant correlation between the expression of FOXP3, IL-10, and TGF-β1 and the abundance of tumor-infiltrating CD4+ CD25+ Foxp3+ Tregs, as inferred by the EPIC algorithm." (PMID 41438510, 2025). "M2 macrophages can promote the expression of anti-inflammatory cytokines such as IL-10, prostaglandin E2, TGF-β, MMP, and VEGF, inhibit dendritic cells and CD8+ T lymphocytes, inhibit immune response, and promote tumor growth and metastasis." (PMID 41562084, 2025). "Blocking C5aR reduced myeloid-derived suppressor cells (MDSCs) in the spleen of 3LL tumor bearing mice and decreased expression of immunosuppressive genes, including ARG1, CTLA-4, IL-6, IL-10, LAG3, and PD-L1 within tumors." (PMID 41300283, 2025). "On top of that, RT-qPCR results revealed the significantly positive correlations between C1QA and IL-10, TGF-β expression levels, highlighting the pro-tumour role of this hub gene in LUAD." (PMID 41171372, 2025). "Second, immunosuppressive factors in the tumor microenvironment, such as TGF-β and IL-10, inhibit the immune response induced by the DC vaccine." (PMID 40333202, 2025). "Tregs can produce the immunosuppressive cytokines IL-10 and TGF-β to deplete IL-2, constituting the CD3+CD4+ subpopulation to suppress the activity of effector T cells and effective anti-tumor immune response." (PMID 40703522, 2025). "IL-10 is an immunosuppressive cytokine, and its reduction by combination therapy, particularly involving NDV, correlates with decreased tumor volume, as discussed further." (PMID 40403026, 2025). "Through secretion of IL-10, TGF-β and IFN-γ, T-bet+ hTregs modulate both innate and adaptive immune responses within the tumor microenvironment (TME)." (PMID 41041322, 2025). "Primarily polarized toward an M2-like phenotype under the influence of cytokines such as IL-10 and TGF-β, TAMs facilitate tumor growth, angiogenesis, metastasis, and immune evasion through multiple mechanisms." (PMID 41142826, 2025). "Significantly, MDSCs facilitate the expansion and recruitment of Tregs by producing IL-10, TGF-β, and by expressing membrane-bound TGF-β (mTGF-β), further dampening the anti-tumor immune response." (PMID 40475782, 2025). "They produce anti-inflammatory cytokines, such as IL-10 and TGF-β, which can suppress the activity of effector immune cells and promote tumor survival." (PMID 40896358, 2025). "These M2 macrophages, characterized by the expression of markers like CD206 and the secretion of anti-inflammatory cytokines such as IL-10 and CCL18, have pro-tumor functions." (PMID 40330466, 2025). "IgA+ B cell clusters, for instance, inhibit CTL expansion and cytotoxicity through IL-10, PD-L1, and Fas ligand (FASL), promoting tumor growth." (PMID 41285707, 2025). "Tumor cells secrete inhibitory cytokines such as interleukin-10 (IL-10) and transforming growth factor-β2 (TGF-β2), which prevent immune effector cells from infiltrating and attacking the tumor." (PMID 41459907, 2025). "Additionally, tumor-associated factors promote the development of tolerogenic dendritic cells (tol-DCs) that express high levels of immunosuppressive molecules and produce IL-10 rather than IL-12, creating an immunosuppressive environment." (PMID 41007774, 2025). "First, M2 TAMs secrete immunosuppressive cytokines (e.g. IL-10, TGF-β) that directly impair the function of effector T cells, weakening anti-tumor immune responses and promoting tumor immune escape." (PMID 40787471, 2025). "The elevated expression of several cytokines such as IL-1β, IL-6, IL-10, TNF-α, and TGF-β has been reported to be involved in tumor initiation and progression in various types of cancer." (PMID 40722593, 2025). "M2d macrophages, activated by adenosine and TLRs, secrete IL-10, TGF-β, and VEGF, promoting angiogenesis and immunosuppression, which enhances tumor progression and metastasis." (PMID 40079009, 2025).